RAB29 (RAB29, member RAS oncogene family)
Description:
The small GTPases Rab are key regulators of intracellular membrane trafficking, from the formation of transport vesicles to their fusion with membranes. Rabs cycle between an inactive GDP-bound form and an active GTP-bound form that is able to recruit to membranes different sets of downstream effectors directly responsible for vesicle formation, movement, tethering and fusion (By similarity). RAB29 is essential for maintaining the integrity of the endosome-trans-Golgi network structure (By similarity). Together with LRRK2, plays a role in the retrograde trafficking pathway for recycling proteins, such as mannose 6 phosphate receptor (M6PR), between lysosomes and the Golgi apparatus in a retromer-dependent manner. Recruits LRRK2 to the Golgi complex and stimulates LRRK2 kinase activity. Stimulates phosphorylation of RAB10 'Thr-73' by LRRK2. Regulates neuronal process morphology in the intact central nervous system (CNS) (By similarity). May play a role in the formation of typhoid toxin transport intermediates during Salmonella enterica serovar Typhi (S.typhi) epithelial cell infection.
Synonyms: RAB7L1; RAB7L
Tractability: Small molecule: a structure with a bound ligand is known. Antibody: UniProt places it where antibodies can reach, with high confidence; its Gene Ontology location is reachable by antibodies, with medium confidence. PROTAC: ubiquitination databases record sites on it; its protein half-life has been measured; a small molecule that binds it is known.
Target class: Enzyme; Hydrolase
Gene: Protein-coding gene on chromosome 1 (205,767,986 to 205,775,482, reverse strand). Ensembl gene ENSG00000117280.
Subcellular location: Cell membrane; Cytoplasm; Cytoplasm, perinuclear region; Golgi apparatus; Golgi apparatus membrane; Golgi apparatus, trans-Golgi network; Vacuole; Cytoplasm, cytoskeleton
Subcellular location (Human Protein Atlas): Nuclear membrane; Vesicles; Cytosol; Nucleoplasm
Pathways (Reactome):
Metabolism of proteins: RAB geranylgeranylation
Gene Ontology:
Molecular function: dynein complex binding; G protein activity; GDP binding; GTP binding; kinase activator activity; kinesin binding; protein binding; small GTPase binding; GTPase activity
Biological process: cellular detoxification; endoplasmic reticulum to Golgi vesicle-mediated transport; Golgi organization; host-mediated perturbation of viral process; mitochondrion organization; negative regulation of neuron projection development; positive regulation of intracellular protein transport; positive regulation of receptor recycling; positive regulation of T cell receptor signaling pathway; protein localization to membrane; regulation of motile cilium assembly; response to bacterium; retrograde transport, endosome to Golgi; synapse assembly; T cell activation; melanosome organization; protein localization to ciliary membrane; intercellular transport; regulation of retrograde transport, endosome to Golgi; vesicle-mediated transport
Cellular component: cis-Golgi network; cytoplasm; cytosol; early endosome; extracellular exosome; Golgi apparatus; intracellular vesicle; mitochondrion; recycling endosome; trans-Golgi network; vacuole; melanosome; cytoplasmic vesicle; cytoskeleton; Golgi membrane; perinuclear region of cytoplasm; plasma membrane; vesicle
Genetic constraint (gnomAD): Loss-of-function variants: 13 observed, 26.24 expected, observed/expected ratio (o/e) 0.5, 90% interval 0.32 to 0.79. The upper end of that interval is the gene's LOEUF score, 0.79, which puts it in group 3 of 6, group 1 being the genes least tolerant of losing a copy. Missense variants: 201 observed, 268.07 expected, observed/expected ratio (o/e) 0.75, 90% interval 0.67 to 0.84. Synonymous variants: 88 observed, 100.92 expected, observed/expected ratio (o/e) 0.87, 90% interval 0.73 to 1.04.
Homologues: Orthologues: chimpanzee RAB29 (100% identical), dog RAB29 (95% identical), rabbit RAB29 (95% identical), guinea pig RAB29 (95% identical), rat Rab29 (94% identical), mouse Rab29 (94% identical), pig RAB29 (94% identical), tropical clawed frog rab29 (64% identical). Paralogues in human: RAB38 (54% identical), RAB32 (53% identical), RAB10 (33% identical), RAB26 (33% identical), RAB6A (33% identical), RAB6B (33% identical), RAB23 (33% identical), RAB33A (33% identical), RAB35 (33% identical), RAB7A (33% identical), RAB31 (33% identical), RAB12 (32% identical), and 56 more.
Diseases named in the same sentence as RAB29 in open-access papers:
RAB29 is named in the same sentence as 15 diseases in open-access papers, as found by Europe PMC text mining. Sharing a sentence is not in itself a finding about the gene and the disease. The quoted sentences say what the papers report.
Parkinson disease (23 papers, 2014 to 2025). A progressive degenerative disorder of the central nervous system characterized by loss of dopamine producing neurons in the substantia nigra and the presence of Lewy bodies in the substantia nigra and locus coeruleus. "Recent genome-wide association studies have identified a link between the RAB29 gene and Parkinson’s disease (PD)." (PMID 41164274, 2025). "Purlyte E., Dhekne H.S., Sarhan A.R., Gomez R., Lis P., Wightman M.,Martinez T.N., Tonelli F., Pfeffer S.R., Alessi D.R. Rab29 activationof the Parkinson’s disease-associated LRRK2 kinase." (PMID 41164274, 2025). "Previous work has indicated that the PARK16 locus, which harbors the gene encoding for Rab29, is involved in Parkinson's, and that Rab29 operates in a common pathway with LRRK2." (PMID 33135724, 2020). "Parkinson's disease predisposing LRRK2 kinase phosphorylates a group of Rab GTPase proteins including Rab29, within the effector‐binding switch II motif." (PMID 29212815, 2018). "A haplotype located near the 5′ region of RAB29 is associated with Parkinson's and epistasis between Rab29 and LRRK2 gene variants has been demonstrated." (PMID 29212815, 2018). "For example, Rab7L1 (also known as Rab29) is one of five genes that is mutated with Parkinson's disease patients that have the PARK16 mutation." (PMID 27474410, 2016). "Similarly, GAK and RAB29 are implicated in mitochondrial dysfunction, which has been linked to urinary biomarker research in Parkinson’s disease." (PMID 40130009, 2025). "The co-expression of LRRK2 and RAB29 in the substantia nigra is of particular interest, as RAB29 is a candidate risk gene for Parkinson’s, is a putative substrate for LRRK2 kinase activity, and may regulate LRRK2." (PMID 36716346, 2023). "Furthermore, variants within the LRRK2 and Rab29 genes synergistically increase Parkinson's risk, and studies in Caenorhabditis elegans indicated that RAB29 (GLO-1) ortholog acts upstream of LRRK2 (LRK-1) in a pathway controlling axon termination." (PMID 32036294, 2020). "Rab29 (also referred as Rab7L1) is a novel Rab protein, which was recently found to mediate bacterial infection, and modify intraneuronal protein sorting and Parkinson's disease risk through interacting with LRRK2." (PMID 24788816, 2014). "Finally, we propose that the new Rab29 monoclonal antibodies we have developed could be exploited to better understand how Parkinson's mutations within the PARK16 locus impact Rab29 protein expression." (PMID 33135724, 2020). "In future work, it will also be important to study how Rab29 expression, localization, and nucleotide binding are controlled in vivo and to explore further, whether overexpression or activation of Rab29 is linked to Parkinson's disease." (PMID 29212815, 2018). "Previous work indicated that Rab29, located within the PARK16 locus mutated in Parkinson's patients, operates in a common pathway with LRRK2." (PMID 29212815, 2018). "Other genetic studies of Parkinson's patient cohorts have found common variants within the LRRK2 and Rab29 genes that function coordinately to increase Parkinson's risk, as human genetic variants at these loci impact Parkinson's risk non‐additively." (PMID 29212815, 2018). "Rab29 localizes to the trans-Golgi network (TGN) and Rab29 knockout mice mimic a phenotype of LRRK2 knockouts – an age-associated lysosomal defect in the kidney." (PMID 29125462, 2017). "However, by gene enrichment analysis of Parkinson’s disease-related genes in the digestive system, RAB29 was mainly enriched in the receptor cycling pathway." (PMID 38240717, 2024). "This will be succeeded by the C. elegans conservation of the RAB29/LRRK2 axis, retromer dysfunction and protein aggregation, pertinently tau and α-synuclein in modelling LRRK2-linked Parkinson’s pathogenesis, with potential implications for modelling the candidate genes of novel GWAS loci." (PMID 34397087, 2021).
Parkinson disease (continued). "RAB29 is contained within the PARK16 locus, which is linked to Parkinson’s disease, even though it remains unclear how variants in this locus influence disease risk." (PMID 32709066, 2020). "The present study focused on Rab29 due to the previous genetic links between Rab29, LRRK2, and Parkinson's disease." (PMID 29212815, 2018). "In mouse melanocytes, which express high levels of Rab38, Rab32, and Rab29, knockdown (or CRISPR knockout) of Rab38, but not Rab32 or Rab29, decreases phosphorylation of multiple LRRK2 substrates, including Rab10 and Rab12, by both endogenous LRRK2 and exogenous Parkinson’s disease-mutant LRRK2." (PMID 37625589, 2023).
melanoma (2 papers, 2022 to 2023). A malignant, usually aggressive tumor composed of atypical, neoplastic melanocytes. "Proteins associated with pigmentation were identified in our targeted-proteomics analysis in melanoma cells, which included Ras-related protein Rab-7L1 (Rab29), L-dopachrome tautomerase (Dct), and 5,6-dihydroxyindole-2-carboxylic acid oxidase (Tyrp1)." (PMID 35745603, 2022). "Rab38 but not Rab32 or Rab29 drives pericentriolar recruitment of exogenous kinase-active LRRK2 in B16 melanoma cells." (PMID 37625589, 2023). "In B16-F10 mouse melanoma cells, Rab38 drives LRRK2 membrane association and overexpressed kinase-active LRRK2 shows striking pericentriolar recruitment, which is dependent on the presence of endogenous Rab38 but not Rab32 or Rab29." (PMID 37625589, 2023).
amyotrophic lateral sclerosis (1 paper, 2021). Amyotrophic lateral sclerosis (ALS) is a neurodegenerative disease characterized by progressive muscular paralysis reflecting degeneration of motor neurons in the primary motor cortex, corticospinal tracts, brainstem and spinal cord. "Functional studies of RAB29 in the presence of C9orf72 hexanucleotide repeat, causative of amyotrophic lateral sclerosis with FTD (ALS-FTD), have illustrated its role in vesicle trafficking." (PMID 34397087, 2021).
Cognitive impairment (1 paper, 2024). Abnormal cognition is characterized by deficits in thinking, reasoning, or remembering. "Defects in Rab7L1 (also known as Rab29) can lead to PD-related neuronal degeneration and mild cognitive impairment." (PMID 39716330, 2024).
infection (4 papers, 2020 to 2025). The state of being infected such as from the introduction of a foreign agent such as serum, vaccine, antigenic substance or organism. "Proteomics identified Rab29 as a TBC1D9 partner; co-immunoprecipitation showed preferential interaction with GTP-dependent Rab29, and the two proteins co-localized following stimulation and infection." (PMID 41306588, 2025). "Furthermore, a recent study showed that trafficking pathways controlled by Rab8A and Rab7L1 (also known as Rab29) are exploited by HIV-1 during trans-infection from DCs to target T cells via VSs." (PMID 34307340, 2021). "Indeed, LRRK2 activation triggered by Rab29 could occur in a specific cell type or tissue, or following a physiological stimulus, stress or infection that we have not investigated." (PMID 33135724, 2020).
bacterial infection (2 papers, 2014 to 2025). "Together, our data support a model in which the TBC1D9 regulates IL-6 expression through a Rab29-mediated pathway, balancing immune responses during bacterial infection." (PMID 41306588, 2025). "In each case, Rab29-KO cells exhibited significantly higher IL-6 mRNA and protein levels compared to WT controls (p < 0.05), suggesting that Rab29 has a broad regulatory effect in reducing IL-6 expression across various bacterial infections." (PMID 41306588, 2025).
metabolic disorders (1 paper, 2023). "The results indicate that RAB29 contributes to metabolic disorders through an immune path." (PMID 37754271, 2023).
RAB29 also shares sentences with these, for which no sentence is quoted: Parkinson's (6 papers); Alzheimer disease (3); cervix carcinoma (1); colorectal cancer (1); depression (1); lung adenocarcinoma (1); neuroblastoma (1); schizophrenia (1).